MINPP1 (multiple inositol-polyphosphate phosphatase 1)
Description:
Multiple inositol polyphosphate phosphatase that hydrolyzes 1D-myo-inositol 1,3,4,5,6-pentakisphosphate (InsP5[2OH]) and 1D-myo-inositol hexakisphosphate (InsP6) to a range of less phosphorylated inositol phosphates. This regulates the availability of these various small molecule second messengers and metal chelators which control many aspects of cell physiology. Has a weak in vitro activity towards 1D-myo-inositol 1,4,5-trisphosphate which is unlikely to be physiologically relevant. By regulating intracellular inositol polyphosphates pools, which act as metal chelators, it may control the availability of intracellular calcium and iron, which are important for proper neuronal development and homeostasis. May have a dual substrate specificity, and function as a 2,3-bisphosphoglycerate 3-phosphatase hydrolyzing 2,3-bisphosphoglycerate to 2-phosphoglycerate. 2,3-bisphosphoglycerate (BPG) is formed as part of the Rapoport-Luebering glycolytic bypass and is a regulator of systemic oxygen homeostasis as the major allosteric effector of hemoglobin.
Synonyms: MIPP; HIPER1; MINPP2; PCH16
Tractability: Antibody: UniProt places it where antibodies can reach, with high confidence; UniProt predicts a signal peptide or a membrane-spanning region; its Gene Ontology location is reachable by antibodies, with medium confidence. PROTAC: ubiquitination databases record sites on it; its protein half-life has been measured.
Gene: Protein-coding gene on chromosome 10 (87,504,875 to 87,553,461, forward strand). Ensembl gene ENSG00000107789.
Subcellular location: Endoplasmic reticulum lumen; Secreted; Cell membrane
Pathways (Reactome):
Metabolism: Synthesis of IPs in the ER lumen
Gene Ontology:
Molecular function: bisphosphoglycerate 3-phosphatase activity; inositol bisphosphate phosphatase activity; inositol hexakisphosphate 3-phosphatase activity; inositol hexakisphosphate 4-phosphatase activity; inositol hexakisphosphate phosphatase activity; inositol pentakisphosphate phosphatase activity; inositol trisphosphate phosphatase activity; inositol-1,3,4,5,6-pentakisphosphate 3-phosphatase activity; inositol-1,3,4,5-tetrakisphosphate 3-phosphatase activity; inositol-1,4,5,6-tetrakisphosphate 6-phosphatase activity; protein binding; acid phosphatase activity; inositol phosphate phosphatase activity; phosphatase activity
Biological process: intracellular monoatomic cation homeostasis; bone mineralization; inositol phosphate metabolic process; ossification
Cellular component: extracellular exosome; extracellular region; endoplasmic reticulum lumen; plasma membrane
Genetic constraint (gnomAD): Loss-of-function variants: 21 observed, 39.53 expected, observed/expected ratio (o/e) 0.53, 90% interval 0.38 to 0.76. The upper end of that interval is the gene's LOEUF score, 0.76, which puts it in group 3 of 6, group 1 being the genes least tolerant of losing a copy. Missense variants: 561 observed, 592.1 expected, observed/expected ratio (o/e) 0.95, 90% interval 0.88 to 1.02. Synonymous variants: 251 observed, 246.64 expected, observed/expected ratio (o/e) 1.02, 90% interval 0.92 to 1.13.
Gene-disease validity (ClinGen):
ClinGen rates the evidence that MINPP1 causes each of these diseases.
pontocerebellar hypoplasia (autosomal recessive): Definitive. Pontocerebellar hypoplasias (PCH) are a rare heterogeneous group of diseases characterized by hypoplasia and atrophy and/or early neurodegeneration of the cerebellum and pons.
Homologues: Orthologues: chimpanzee MINPP1 (99% identical), pig MINPP1 (88% identical), dog MINPP1 (87% identical), guinea pig MINPP1 (87% identical), rat Minpp1 (83% identical), mouse Minpp1 (82% identical), tropical clawed frog minpp1 (51% identical), zebrafish minpp1b (42% identical), zebrafish minpp1a (41% identical), Drosophila melanogaster Mipp2 (24% identical), Drosophila melanogaster Mipp1 (24% identical).
Diseases named in the same sentence as MINPP1 in open-access papers:
MINPP1 is named in the same sentence as 26 diseases in open-access papers, as found by Europe PMC text mining. Sharing a sentence is not in itself a finding about the gene and the disease. The quoted sentences say what the papers report.
hepatocellular carcinoma (5 papers, 2021 to 2025). A malignant tumor that arises from hepatocytes. "The P protein (HBp) encoded by the HBV virus interacts with FOXO3a to promote the activity of miR-30b-5p in HBV-positive hepatocellular carcinoma, and MINPP1 inhibits tumour cell proliferation." (PMID 37965449, 2023). "MINPP1 decreases the number of hepatocellular carcinoma cells via this glycolytic bypass, and it is believed that, in the future, this molecule will emerge as a synergistic drug target for hepatocellular carcinoma therapeutics." (PMID 37965449, 2023). "The enzyme, MINPP1, regulates the catalyzation from 2, 3‐BPG to 2‐PG, participates in glycolytic bypass, and inhibits cancer cell growth in hepatitis B virus‐related hepatocellular carcinoma." (PMID 39517120, 2025). "In the study reporting these findings, a new tumorigenic axis, HBp/FOXO3a/miR-30b-5p/MINPP1, was discovered, and it facilitated the regression of HBV-positive hepatocellular carcinoma through a glycolytic bypass that is specific to HBV-associated hepatocellular carcinoma." (PMID 37965449, 2023).
breast carcinoma (2 papers, 2011 to 2022). "This study explored Minpp1 heterogeneity and identified a Minpp1 isoform-2 in extracellular vesicles (exosomes) isolated from a human breast cancer cell line, MCF-7." (PMID 35235602, 2022).
pontocerebellar hypoplasia (2 papers, 2020 to 2021). "Taken together, we present MINPP1 as a novel autosomal recessive pontocerebellar hypoplasia gene." (PMID 33168985, 2021).
androgen insensitivity syndrome (1 paper, 2021). Androgen insensitivity syndrome (AIS) is a disorder of sex development (DSD) characterized by the presence of female external genitalia, ambiguous genitalia or variable defects in virilization in a 46,XY individual with absent or partial responsiveness to age-appropriate levels of androgens. "Furthermore, in family 3 we identified a variant in the androgen receptor gene AR (OMIM *313700) that may lead to the androgen insensitivity syndrome (OMIM # 300068) and thus explain the micropenis regardless of MINPP1." (PMID 33168985, 2021).
liver cancer (1 paper, 2021). An epithelial or non-epithelial malignant neoplasm that arises from the liver. "Results showed that MINPP1 inhibits HCC development, but this was limited to HBV-positive HCC and not other liver cancers." (PMID 33390177, 2021).
microcephaly (1 paper, 2024). A congenital or acquired developmental disorder in which the circumference of the head is smaller than normal for the person's age and sex. "Two other ER enzymes have been directly linked to microcephaly: POFUT1 and MINPP1." (PMID 39115595, 2024).
prostate carcinoma (1 paper, 2016). A carcinoma that arises from epithelial cells of the prostate gland. "Similarly, MCPH1 and MINPP1 exhibited frequent CNLs in the same prostate cancer cohort with PTEN." (PMID 27929028, 2016).
tumor (10 papers, 2013 to 2025). "The results suggest a potential role for exosome-associated Minpp1 isoform-2 in promoting tumor cell growth by preventing anti-proliferative actions of InsP6." (PMID 35235602, 2022). "But miRNA‐30b‐5p and MINPP1 greatly expanded, tumor cell migration enhanced, and glycolytic bypass encouraged, once the hepatitis B virus (HBV) entered these cells." (PMID 38967113, 2024). "Overall, the data support the possibility that an extracellular form of enzymatically active Minpp1 isoform-2 mitigates any anti-proliferative actions of extracellular InsPs, thereby also impacting the makeup of the tumor microenvironment." (PMID 35235602, 2022). "HE and PCNA analysis of tumor pathological tissue further revealed that overexpression of MINPP1 gene inhibits the proliferation of tumor cells." (PMID 33390177, 2021). "It was witnessed that the growth, volume, and weight of tumor lumps in the xenograft mouse model were significantly decreased in mice injected with cells overexpressing MINPP1 as compared to the control groups." (PMID 33390177, 2021). "Thus, exosomal secretion of an isoform of MinPP1 represents a novel mechanism of TME modulation by metabolic reprogramming supporting tumor progression." (PMID 40941035, 2025). "MINPP1 is a tumor suppressor, which can inhibit tumor proliferation and metastasis." (PMID 36672482, 2023). "If this hypothesis turns out true, it would also then mean that the Minpp1 enzymatic activity observed earlier in tumor cell culture media could well be due to Minpp1 isoform-2." (PMID 35235602, 2022). "However, once HBV was introduced into these cells, miRNA-30b-5p/MINPP1 significantly enhanced the proliferation, migration of tumor cells, and promoted the glycolytic bypass." (PMID 33390177, 2021). "EML4‐ALK and MINPP1 & PAPSS2‐PTEN fusions were found to be present in tumor tissue and blood." (PMID 33225619, 2021). "Coupling of cytotoxic substances to the MINPP1-sensitive 3-phosphate group of InsP6 may enable to transport cytostatica into tumour cells and slowly release them from its carrier." (PMID 24050387, 2013). "Thus, inhibition of the Minpp1 isoform-2 enzyme could inhibit ECM’s protective potential, making Minpp1 isoform-2 an attractive target for drug therapy to restrict tumor invasion." (PMID 35235602, 2022). "Therefore, and as suggested for PTEN’s expression in the tumor’s microenvironment, the expression of Minpp1 isoform-2 enzyme in exosomes could imply an essential role in the evolution of ECM and tumor cells during metastasis." (PMID 35235602, 2022). "Thus, targeting exosomal MinPP1 could restore InsP6-mediated tumor suppression." (PMID 40941035, 2025). "NGS results revealed that both EML4‐ALK fusion and MINPP1 and PAPSS2‐PTEN fusion were present in the patient's tumor tissue and ctDNA in blood." (PMID 33225619, 2021). "Thus, packaging enzymatically active Minpp1 isoform-2 into exosomes could facilitate the exogenous transfer of Minpp1 isoform-2 from one cell to another or assist in ECM remodeling by protecting tumor cells against the anti-proliferative actions of any extracellular InsPs." (PMID 35235602, 2022). "The reverse effect of MINPP1 expression on the proliferation and invasion of HBV-positive liver cell lines leaded to a hypothesis that MINPP1 may suppress tumor growth in HBV-positive HCC tissue." (PMID 33390177, 2021). "MINPP1 is down-regulated in HBV-positive HCC and could inhibit the proliferation and migration of the tumor cells." (PMID 33390177, 2021). "Interestingly, five genes with concordance between CNLs and down-regulation were observed in more than 50 tumor samples, including MTAP (216 samples), PTEN (143 samples), MCPH1 (86 samples), SMAD4 (63 samples), and MINPP1 (51 samples)." (PMID 27929028, 2016). "In addition, MINPP1 is controlled in HCC and may inhibit the migration and proliferation of tumor cells." (PMID 38967113, 2024).
infection (3 papers, 2020 to 2024). The state of being infected such as from the introduction of a foreign agent such as serum, vaccine, antigenic substance or organism. "If cells expressing MINPP1 are less susceptible to infection, then the fraction of GFP-positive cells that are also APC positive (virus transduced) should be less than the fraction GFP-negative cells that are APC positive." (PMID 32776974, 2020). "In any case, the fact that MINPP1 reduced the infectability of IPPK-KO cells further supports the conclusion that infection by MLV depends upon the maintenance of proper IP5 and/or IP6 levels in target cells." (PMID 38464197, 2024). "To test the role of IP5 depletion in susceptibility of target cells, we next transduced the MINPP1-IRES-GFP vector or an empty IRES-GFP control into HEK293FT or IPPK-KO cells, and then tested their susceptibility to infection." (PMID 32776974, 2020).
neurological disorders (3 papers, 2020 to 2025). "To assess how frequently MINPP1 mutations could be involved in PCH, we explored two other cohorts of pediatric cases with neurological disorders." (PMID 33257696, 2020).
MINPP1 also shares sentences with these, for which no sentence is quoted: glioblastoma (4 papers); cancer (3); Alzheimer disease (1); atrial septal defect (1); cardiovascular disorder (1); cervical cancer (1); coinfection (1); colorectal adenocarcinoma (1); fibrosarcoma (1); gingivitis (1); Hypertonia (1); Hypotonia (1); neurodevelopmental disorder (1); Patent ductus arteriosus (1); Patent foramen ovale (1); periodontitis (1).